BCL2 (BCL2 apoptosis regulator)
Diseases named in the same sentence as BCL2 in open-access papers (continued):
Sharing a sentence is not in itself a finding about the gene and the disease.
chronic lymphocytic leukemia (continued). "Additionally in 2019, a novel small-molecule inhibitor of apoptosis (via Bcl-2 inhibition), Venetoclax (Venclexta, Venclycto), was approved by the FDA (EMA, in 2020) for the treatment of chronic lymphocytic leukemia (CLL), small lymphocytic lymphoma (SLL) and acute myeloid leukemia (AML)." (PMID 33297561, 2020). "Among the different strategies that have been developed to inhibit BCL-2, BH3-mimetics have emerged as a novel class of compounds with favorable results in different clinical settings, including chronic lymphocytic leukemia (CLL)." (PMID 29747654, 2018). "WSU-CLL and ESKOL cell lines and lymphocytes from patients affected by B-cell chronic lymphocytic leukemia were killed by RSV through apoptosis while the iNOS and Bcl-2 anti-apoptotic proteins were down-regulated." (PMID 24658441, 2014). "A recently developed modified BCl-2 inhibitor, ABT-199, shows high selectivity towards BCL-2 without inhibiting BCL-XL or BCL-w and is currently approved for chronic lymphocytic leukemia." (PMID 30206207, 2018). "Chronic lymphocytic leukaemia cells were sensitive to BIM and BAD peptides but not to HRK or MS-1, consistent with their BCL-2-addiction." (PMID 26954718, 2016). "In addition, the expression of Bcl-2 can be inhibited by BDA-366 in HT Bcl2 and G326 cells but not other chronic lymphocytic leukemia cells." (PMID 37237269, 2023).
glioma (401 papers, 2002 to 2026). A benign or malignant brain and spinal cord tumor that arises from glial cells (astrocytes, oligodendrocytes, ependymal cells). "Despite XIAP and BCL-2 being anti-apoptotic, blocking them is linked to increased apoptosis and reduced glioma survival." (PMID 40739397, 2025). "It is also reported in the literature that the BCL2 gene is associated with treatment resistance and tumor recurrence in gliomas." (PMID 38957232, 2024). "Given that BCL2 overexpression has been implicated in various cancer types as a driver of resistance, the drug’s efficacy in high-risk glioma patients underscores the importance of apoptosis modulation in this subgroup." (PMID 39434883, 2024). "Bcl-2-associated X protein (Bax) and Bcl2 have been demonstrated to promote apoptosis in U251 and A172 glioma cells by increasing caspase-3 and 9 expressions." (PMID 36013319, 2022). "The proapoptotic effects of miR-136 on glioma cells in connection with the induction of chemotherapy have been revealed to have been associated with Bcl-2, a well-known apoptosis inhibitor, indicating the tumor-suppressive role of miR-136 in glioma." (PMID 35083134, 2021). "A recent review showed that Bcl-2 hyperexpression in tumor cells is associated with good prognosis in colorectal, breast, non-small cell, glioma, and gastric cancers." (PMID 32341393, 2020). "In 2017, it was determined that an up-regulated expression of CRNDE induces EGFR (Epidermal Growth Factor Receptor) activation, resulting in poor survival in glioma patients and apoptosis inhibition through increased Bcl2/Bax (BCL2 Associated X) ratio." (PMID 30583549, 2018). "These genes attracted our attention because Bcl-2 has been reported to be a direct target of miR-136-5p, while both Wnt2 and Bcl-2 have been linked to the pathogenesis of glioma." (PMID 29152149, 2017). "Bex2 overexpression is associated with increased activation of the Bcl-2/NF-κB pathway in primary breast tumors and glioma cells." (PMID 25612294, 2015). "The protein expression levels of Bcl-2 have previously been shown to be associated with apoptosis in numerous cell types, including glioma cells." (PMID 25777142, 2015). "The down-regulation of anti-apoptotic protein Bcl-2 and activation of caspase 9/3-dependent pathway were associated with tumor cell growth inhibition, especially in glioma cells." (PMID 24303074, 2013). "As a key element in cancer development, the miRNA/Bcl-2 signaling has been widely identified in different types of human disease, such as miR-34a in age-related hearing loss, miR-21 in gastrointestinal stromal tumor, miR-181b-5p in glioma and miR-497 in MM." (PMID 34980181, 2022). "Moreover, the authors showed that CRNDE knockdown suppresses glioma cell growth in vitro and in vivo, and is associated with decreased Bcl2/Bax ratio." (PMID 34298634, 2021). "Theoretically, an altered ratio of Bcl-2/Bax causes downstream activation of caspase cascades (such as caspase 8), ultimately leading to the activation of cleaved caspase 348–50, which was observed in glioma cells after treatment with α-m-Dox/M." (PMID 33116114, 2020). "To investigate whether Bcl2 inhibition caused by ALO is associated with cell apoptosis in glioma cells, we examined the apoptosis rate in response to ALO and ABT199 treatment." (PMID 31534865, 2019). "In addition, clinical data indicated that the expression of miR-153-3p was significantly negatively associated with BCL2 in radioresistance of glioma samples." (PMID 30537994, 2018).
glioma (continued). "The current study aimed to determine whether miR-153-3p associated with radioresistance in glioma and reveal its biological function and the correlation with BCL2." (PMID 30537994, 2018). "In addition, western blot analysis was performed to determine the expression levels of the following apoptosis-associated proteins in glioma cells: Bcl-2, Bax, Bcl-xL, cleaved-PARP, cleaved-caspase-3, AKT and p-AKT." (PMID 25777142, 2015). "High-grade gliomas have a higher WT1 expression level compared with low-grade gliomas, and BCL2 is associated with the higher tumour grades, poorer patient survival, and the conferring of treatment resistance through its own action and the action of other gene family members." (PMID 24602166, 2014). "In glioma cell lines, miR-181d suppressed tumor growth by lowering the levels of both K-Ras and Bcl-2, while in glioblastoma cells, miR-451 reduced the levels of Cyclin D1 and Bcl-2, causing growth arrest and enhancing cell death." (PMID 23325049, 2013). "Similarly, ceramide has been reported to cause apoptotic cell death by altering the Bax/Bcl2 ratio which triggers cytochrome C release from the mitochondria and results in activation of the caspase-9/-3 cascade in C6 glioma cells." (PMID 22973882, 2012). "We have tested this hypothesis by establishing cell lines, which stably express transgenes encoding either for human Bax or Bcl-2 in a rat glioma model and analyzed the effects of these transgenes on the in vitro and in vivo growth of these cell lines." (PMID 15331018, 2004). "Additionally, they demonstrated that curcumin might promote glioma cell apoptosis by causing a significant decreases in the expression of Bcl-2, an anti-apoptotic effector and direct target of Hh signaling." (PMID 39507759, 2024). "This study explored whether EMAP-II can enhance the cytotoxic effects of TMZ on glioma stem cells (GSCs) and the possible mechanisms associated with Bcl-2/adenovirus E1B 19 kDa protein-interacting protein 3 (BNIP3)-mediated mitophagy facilitated by miR-24-3p regulation." (PMID 29632473, 2018). "Additionally, uPAR downregulation might induce apoptosis in gliomas through calcineurin redistribution, its reduced association with Bcl-2, and the dephosphorylation of the Bcl2-associated death promoter (BAD)." (PMID 29179464, 2017). "Bcl-2, a mitochondrial membrane-associated protein, is a target of miR-181 that mediates miR-181a-mediated Neuro-2a cell death upon oxidative stress, miR-181a-triggered mitochondrial dysfunction and astrocyte death upon glucose deprivation, and miR-181d-induced glioma cell apoptosis." (PMID 28053821, 2016). "Mechanistically, in glioma xenografts, MF-induced cell death involves apoptosis via increased caspase-3 and Bax proteins and decreased Bcl-2 expression." (PMID 41439468, 2026). "Overexpression of BCL-2 in glioma cells is known to evade apoptosis, contributing to drug resistance." (PMID 40739397, 2025). "The combination treatment of resveratrol and temozolomide demonstrates synergistic effects by inhibiting MGMT expression and downregulating the STAT3/Bcl-2/survivin signaling pathway, which leads to increased apoptosis and cell cycle arrest in glioma cells." (PMID 41009025, 2025). "In vitro studies have shown that berberine induces apoptosis in glioma cells by reducing Bcl-2 protein expression." (PMID 40286187, 2025). "As it was mentioned before, we had discovered that under specific conditions of blocking the intracellular survival pathways, the complex of Bcl-2 and beclin-1 proteins was a specific trigger for apoptotic dominant glioma cell elimination." (PMID 41511337, 2025).
glioma (continued). "In glioma, miR-181a-5p upregulation promotes G1-phase arrest by targeting caspase-9, Bcl-2, and SIRT1, ultimately inhibiting cell proliferation." (PMID 40863219, 2025). "Our experimental studies show that combining sorafenib with temozolomide or LY294002 or furanocoumarins enhances autophagy and apoptosis in T98G cells, while dihydroartemisinin suppresses MEK/ERK phosphorylation and Bcl-2/Mcl-1 in different glioma models." (PMID 41511337, 2025). "A well-known example, described in malignant glioma cells by our team before, of this crosstalk is the interaction between the anti-apoptotic protein Bcl-2 and the autophagy regulator beclin-1." (PMID 41511337, 2025). "It activates the Ca2+/calmodulin-dependent protein kinase II (CaMKII) pathway, inhibits mitochondrial apoptosis by reducing the Bax/Bcl-2 ratio, and promotes glioma cell survival." (PMID 40823088, 2025). "Antisense BCL-2 expression significantly increased cisplatin cytotoxicity and reduced glioma cell survival." (PMID 40739397, 2025). "In glioma cells, overexpression of Bcl-2 has been shown to suppress autophagy mediated by the Beclin1 and Akt-mTOR pathways." (PMID 40535121, 2025). "The levels of survivin and Bcl-2, which are active in cell proliferation and maintenance of gliomas and are target genes of the STAT3 pathway, were decreased in Res/TMZ-treated cells." (PMID 41009025, 2025). "A dendrimer‐entrapped AuNPs (Au DENPs) were successfully used as a platform for the delivery of VEGF or B‐cell lymphoma/leukemia 2 protein (BCL‐2) siRNA into a human glioma cell line." (PMID 40546878, 2025). "Intracranial injection of folate-targeted nanocarriers incorporating siRNA was applied to downregulate B-cell lymphoma 2 (BCL-2) in orthotropic glioma in rats." (PMID 41516252, 2025). "We then discuss the possible role of hypomethylating agents and BCL2 inhibitors in patients with recurrent IDH-mutant gliomas." (PMID 38957232, 2024). "Levels of pro-apoptotic proteins (including Bad and cleaved-caspase-9) were increased, while the expressions of anti-apoptotic markers(e.g., MMP-9, MMP-2, and Bcl-2) were decreased in PQR309-treated glioma models." (PMID 38555280, 2024). "Glioma cells frequently demonstrate overexpression of anti-apoptotic proteins (e.g., Bcl-2, Bcl-xL) and deactivation of pro-apoptotic proteins (e.g., Bax, Caspase family)." (PMID 39184045, 2024). "ABT.263 (navitoclax) as a Bcl-xL/Bcl-2/Bcl-w inhibitor, potentiated caspase-dependent cell death in response to 2-deoxyglucose or its combination with metformin in pediatric glioma." (PMID 38686055, 2024). "In lung, glioma, and BC cells, it has been detected that overexpressing Bcl-2 accelerates migration and invasion." (PMID 38223131, 2024). "The western blot results showed that the protein level of BAX was up-regulated and that the protein level of Bcl-2 (an anti-apoptotic factor) was reduced by WZ-3146 treatment in glioma cell lines (U251 and LN229)." (PMID 38937742, 2024). "Simultaneously, LRIG1 modulates the Bcl-2 and Topo-2 levels, rendering glioma cells more responsive to temozolomide (TMZ) treatment." (PMID 38790164, 2024). "The results showed that the levels of Bcl-xL and Bcl-2 decreased in glioma cells after AMT treatment, while the expression of pro-apoptotic proteins Bax and Bak was promoted." (PMID 39548081, 2024). "FOSL1 and JUN are the downstream factors in the PI3K/Akt pathway, and they can form a stable heterodimer known as AP-1, a transcriptional activator that can influence glioma behavior, reflected by elevated levels of phenotype markers BCL2 and PCNA." (PMID 39554845, 2024). "Given that oxidative stress can regulate the apoptosis of glioma cells via the Caspase pathway, we further investigated the expression levels of apoptosis-related proteins, including caspase-7, Bcl-2, and Bax, in circFOXO3-KD and NC cells." (PMID 39449966, 2024).
glioma (continued). "Experimental downregulation of MDA9 in anoikis-resistant glioma cells resulted in sustained levels of autophagy and inhibition of BCL-2 phosphorylation, leading to anoikis of tumor stem cells." (PMID 39062119, 2024). "Gliomas, aggressive brain tumors with high BCL-2 levels, pose a significant therapeutic challenge due to their resistance to conventional treatments and high recurrence rates." (PMID 38685028, 2024). "The induction of apoptotic cell death in human glioma (U-87MG) cells was seen upon treatment with curcumin, which was found to modulate the activities of caspase 3 and Bcl-2." (PMID 38978121, 2024). "Previous studies have confirmed the ability of ATOR to inhibit Bcl-2 and Caspase-3 expression thereby inhibiting glioma angiogenesis and ultimately inhibiting glioma cell progression." (PMID 39726023, 2024). "This supports the idea that the effect of AQP8 on apoptosis in glioma cells is related to the Bcl-2/Bax ratio." (PMID 37280594, 2023). "It was also reported to induce enhanced mRNA levels of caspases 3, 8, and 9 and reduced the mRNA levels of Bcl-2 in glioma cells." (PMID 37259418, 2023). "Recently, Dequalinium showed promising results in vitro and in vivo, inhibiting the growth and proliferation of human glioma cells by decreasing BCL-2 expression." (PMID 37193964, 2023). "Conclusions: “Switching” between apoptosis and autophagy using PI3K and Raf inhibitors with Bcl-2:beclin-1 complex formation opens new therapeutic perspectives against gliomas." (PMID 38067099, 2023). "Multiple molecular aberrations contribute to TRAlL-resistance of glioma, such as lower expression of caspase-8, overexpression of c-FLIP, Bcl-2 and Bcl-xL or loss or structural alterations of TRAIL-R1, TRAIL-R2, Apaf-1, Smac and Bid." (PMID 37158962, 2023). "Functional analysis in human gliomas suggested that HOXD9 deletion induced apoptosis via downregulation of anti-apoptotic factor B-cell lymphoma-2 (BCL-2) and upregulation of tumor necrosis factor-related apoptosis-inducing ligand (TRAIL)." (PMID 36907878, 2023). "This study aimed to investigate the regulatory role of Aldo-keto reductase family 1 member B1 (AKR1B1) in glioma cell proliferation through p38 MAPK activation to control Bcl-2/BAX/caspase-3 apoptosis signaling." (PMID 37185746, 2023). "In conclusion, AKR1B1 regulated glioma cell proliferation through the involvement of p38 MAPK-induced BAX/Bcl-2/caspase-3 apoptosis signaling." (PMID 37185746, 2023). "The balance between pro-apoptotic BAX and anti-apoptotic Bcl-2 proteins is known to regulate caspase-3 activity and apoptosis in glioma cells." (PMID 37185746, 2023). "The aim of this research was to investigate the role of Bcl-2:beclin-1 complex in glioma cell elimination through the combined action of LY294002 and sorafenib." (PMID 38067099, 2023). "FASN inhibitors induce apoptosis in glioma cells by activation of caspases 3 and downregulation of Bcl-2 protein." (PMID 38139462, 2023). "At a dose of 36 M, ferulic acid (FA) causes cellular apoptosis and decreases the expression of Bcl‐2, ERK1/2 and c‐Myc while increasing the expression of PARP‐1 cleavage in the glioma cell line U‐87MG." (PMID 37675821, 2023). "As for the miR-30c-5p, miR-30c-5p inhibitors restored Bcl2 expression and inhibited apoptosis and increased colony and migration characteristic of glioma." (PMID 38012562, 2023). "Several strategies, such as small molecule inhibitors, gene therapy, and immunotherapy, have been explored to modulate BAX and Bcl-2 expression and restore caspase-3 activity in glioma cells, with promising results in preclinical studies." (PMID 37185746, 2023). "The activity of compound 3a was also investigated in glioma models, and it sensitized U251 and U343 glioma cells to treatment with the Bcl-2 inhibitors (-)-gossypol (AT-101) and ABT-737." (PMID 36835501, 2023).